NF1 (neurofibromin 1)
Diseases named in the same sentence as NF1 in open-access papers (continued):
Sharing a sentence is not in itself a finding about the gene and the disease.
nerve sheath tumors (24 papers, 2012 to 2025). "Neurofibromatosis 1 (NF1) is a genetic disorder that predisposes patients to developing nerve sheath tumors that are difficult to treat." (PMID 38136356, 2023). "The protocol below describes the specific steps for single-cell RNA sequencing of a single-cell suspension obtained from fresh NF1-associated nerve sheath tumors." (PMID 37167059, 2023). "The key features of various NF1-associated nerve sheath tumors are summarized according to the classification proposed by the National Institute of Health (NIH) in 2016." (PMID 33850471, 2021). "This approach revealed biological patterns that underlie different NF1 nerve sheath tumor types and candidate genes and cellular signatures associated with NF1 tumor heterogeneity." (PMID 32098059, 2020). "Based on 2D and 3D in vitro results, AZD8055/PD0325901 or AZD8055/BET bromodomain inhibitors combination efficacy now needs to be empirically tested in rigorous models in vivo to support these combination strategy for NF1-associated nerve sheath tumors." (PMID 26840085, 2016). "Our approach demonstrates improved accuracy for detection of high-risk NF1 nerve sheath tumors that may undergo malignant transformation and it can be translated to the clinic for early diagnosis and possibly prevention of MPNST." (PMID 40585258, 2025). "In light of this clinical need and the extensive evidence of specific molecular profiles across the spectrum of NF1-associated nerve sheath tumors, there is a strong need to incorporate these molecular alterations into an integrated diagnostic scheme to maximize clarity and accuracy in diagnosis." (PMID 39500722, 2025). "We performed a comparison with datasets of genes from GDC Data Portal and cBio Portal, derived from patients affected with the nerve sheath tumors, and a list of genes associated with NF1-related MPNSTs from the scientific literature search (searched with the “NF1 or MPNST” MESH terms)." (PMID 39409151, 2024). "We differentiate NF1-associated PNSTs by generating fragment-based features from cfDNA which allow us to granularly distinguish between non-malignant, pre-malignant, and frankly malignant forms of nerve sheath tumors." (PMID 38293154, 2024). "Schwann cells are considered the cell-of-origin of NF1-associated nerve sheath tumors." (PMID 37167059, 2023). "In conclusion, this work proposed a short list of testable hypotheses involving specific biological signatures for NF1-deficient nerve sheath tumors." (PMID 32098059, 2020). "Somatic NF1 pathogenic mutations in tumours occur in several settings: In NF1 patients, a second NF1 hit occurs in NF1 associated nerve sheath tumours besides a germline NF1 pathogenic variant (first hit) and leads to biallelic inactivation of NF1 following the Knudson two-hit hypothesis." (PMID 34997843, 2022). "Previous genomic profiling studies have demonstrated that many NF1 nerve sheath tumors (MPNST being the exception) are genetically quiet and lack specific signatures that are predictive of drug response." (PMID 32098059, 2020). "Verification of these mechanisms in in-vitro and in-vivo models of nerve sheath tumors as well as human NF1 nerve sheath tumor tissue needs active and extensive experimental work." (PMID 32098059, 2020). "Taken together, these and other studies suggest that an integrative approach that combines multiple transcriptomic and genomic datasets might be well poised to identify new therapeutic avenues in MPNSTs and other NF1-related nerve sheath tumors." (PMID 32098059, 2020). "The MDCT and VR study was better than MR in evaluating the findings of NF-1 in 24 of 36 patients for a total of 40 findings, including the following categories A) bony abnormalities (n = 12), B) abnormal spinal curvature (n = 10), C) nerve sheath tumors (n = 3), and D) instrumentation (n = 15)." (PMID 25852768, 2014).
nerve sheath tumors (continued). "Primary osseous dysplasia of the skull without detectable adjacent (peripheral) nerve sheath tumour is a long-standing and well-known peculiarity of NF1." (PMID 28401031, 2017).
rhabdomyosarcoma (24 papers, 2010 to 2025). A rare aggressive malignant mesenchymal neoplasm arising from skeletal muscle. "For example, there was the deletion of the NF1 gene in pediatric rhabdomyosarcoma; 20% cases with mutation in the NF1 gene were observed in 86 liposarcomas using the whole-exome sequencing." (PMID 35559021, 2022). "Other frequently altered genes are RB1 and MYC (a well-known oncosuppressor and oncogene, respectively), NF1 (known for being often mutated in neural tumors), and PAXX (often fused with FOXO1 in alveolar rhabdomyosarcomas)." (PMID 40725011, 2025). "A major goal was to design a promoter specific for rhabdomyosarcoma cells over myogenic cells, and while we increased rhabdomyosarcoma specificity with our ∆MEF3/NF1 MYOGENIN promoter, there remains residual toxicity in myoblasts." (PMID 32973362, 2021). "There are a number of other malignant tumour types that have been found to harbour NF1 alterations including neuroendocrine prostate cancer (24%), myxofibrosarcomas (10.5%) and pleomorphic liposarcomas (8%), pancreatic cancer (11%), gastric adenocarcinoma (10%) and rhabdomyosarcoma (7%)." (PMID 28637487, 2017). "A number of other tumours are also associated with NF1, including optic gliomas, juvenile myelomonocytic leukaemia (JMML), benign or malignant phaeochromocytomas, gastrointestinal stromal tumours, glomus tumours, juvenile xanthogranulomas, rhabdomyosarcomas and lipomas." (PMID 28637487, 2017).
developmental delay (23 papers, 2012 to 2025). "Type-1 deletions are frequently associated with overgrowth, global developmental delay, cognitive disability and dysmorphic facial features which are uncommon in patients with intragenic pathogenic NF1 gene variants." (PMID 34535841, 2021). "The developmental delay in patient 310221 reported here appears to be within the range of developmental delays frequently seen in children with NF1 and intragenic NF1 mutations." (PMID 34681033, 2021). "Nevertheless, the developmental delays observed in children with NF1 and intragenic NF1 mutations are much less severe than the global developmental delays affecting multiple areas seen in many children with large NF1 microdeletions." (PMID 34681033, 2021). "Recently, three reports have associated NF1 with developmental delay." (PMID 25580325, 2014). "Besides the prominent hallmarks of NF1, patients with NF1 microdeletions frequently exhibit specific additional clinical manifestations like dysmorphic facial features, macrocephaly, overgrowth, global developmental delay, cognitive disability and an increased risk of malignancies." (PMID 37686382, 2023). "Developmental delay (30.0% vs 3.1%, p = 0.036), PN (28.6% vs 5.7%, p = 0.030), and NF1+ (71.4% vs 30.2%, p = 0.011) was more commonly observed in familial cases." (PMID 35093157, 2022). "The developmental delay observed in patient 310221 was much less severe than the global developmental delay frequently observed in children with type 1 or very large atypical NF1 microdeletions." (PMID 34681033, 2021). "Severe global developmental delay in language and motor skills has been observed in 28 (93%) of 30 children with NF1 microdeletions." (PMID 34681033, 2021). "Only for seven patients with group #2 atypical NF1 deletions has information about the presence of developmental delay been published." (PMID 34681033, 2021). "Global developmental delay was observed in 28 (93%) of 30 children with NF1 microdeletions investigated." (PMID 32533297, 2020). "Remarkably, among these 160 patients with suggested Sotossyndrome and overgrowth was a 4-year-old girl with dysmorphic facial features, twoCALS and developmental delay who was found to have an NF1 microdeletion." (PMID 28213670, 2017). "We found 5 cases with an NF1 gene deletion in patients with various severe conditions, such as developmental delay, seizures, and early onset skin/subcutaneous tissue disorders." (PMID 24789688, 2014). "Given previous reports of delayed development in the NF1 cohort by 40 months, early clinical interventions strategies to promote sleep hygiene may be beneficial to optimise developmental outcomes." (PMID 35936291, 2022). "Comparative analysis of such atypical NF1 deletions suggests that SUZ12 hemizygosity is likely to contribute significantly to the reduced cognitive abilities, severe global developmental delay and facial dysmorphisms observed in patients with type 1 NF1 deletions." (PMID 34681033, 2021). "Alternatively, the developmental trajectory of gait differences that we observed in Nf1+/R681X mice may vary in timing between models, with some showing more prolonged developmental delays than others." (PMID 33743598, 2021). "Thus, genes located telomeric to NF1, and not encompassed by the 698 kb atypical NF1 deletion of patient 310221, may contribute to the significantly reduced FSIQ and severe global developmental delays frequently seen in patients with type 1 NF1 deletions." (PMID 34681033, 2021). "Not much is known about the areas of developmental delay and their progression over time in other patients with atypical NF1 deletions of group #2, which encompass only a subset of genes within the type 1 NF1 microdeletion region." (PMID 34681033, 2021). "Nevertheless, neither patient showed the global, very severe developmental delay in numerous areas as frequently observed in children with type 1 NF1 deletions." (PMID 34681033, 2021).
developmental delay (continued). "Patient 310221 does not show features frequently seen in patients with type 1 NF1 deletions, such as global severe developmental delay, cognitive disability, overgrowth and facial dysmorphism, which are all detectable at a very young age." (PMID 34681033, 2021). "In a disease context, NF1 microduplications have been observed in 14 unrelatedindividuals identified from among a total of 77,902 patients who were investigatedby array CGH due to developmental delay." (PMID 28213670, 2017). "This was shown in an expanded map of almost 30.000 children suffering from developmental delay in which NF1 duplications were not described among the 70 most common copy number variations." (PMID 25580325, 2014). "Furthermore, the clinical phenotype in very young patients with NF1 microdeletions pertaining to cognitive abilities, developmental delay and the presence of autistic symptomatology has not been systematically investigated as yet." (PMID 32533297, 2020). "Also, the boy (#15) with a 1.5 duplication at 17q11.2 encompassing NF1 gene did not present developmental delay or seizures allegedly reported in patients with such duplication." (PMID 27629806, 2017).
learning disabilities (22 papers, 2003 to 2024). "In our cohort, we found a higher prevalence of learning disabilities in patients with NF1 frameshift mutations." (PMID 35885913, 2022). "Moreover, accumulating reports have linked genetic defects that either increase or decrease Ras/Rap signaling with several mental disorders associated with learning disability, such as NF1." (PMID 37446790, 2023). "NF1 is one of the most common single-gene causes of learning disabilities; studies on working memory and electrophysiology in NF1 mouse models (Nf1 heterozygous null mutants; Nf1+/−) have demonstrated that the NF1 mutation causes spatial learning disabilities and attention deficits." (PMID 28673309, 2017). "As neurological issues have also been observed in Weaver and other overgrowth syndromes, this argues in favour of the implication of SUZ12 in learning disabilities in NF1 deletion patients." (PMID 38448973, 2024). "As a result, patients with NF-1 develop malignancies and complex cognitive symptoms that include learning disabilities, attention deficit disorder and motor coordination problems." (PMID 23056445, 2012). "However, the study did show a positive correlation between the length of NF1 locus deletion and learning disabilities." (PMID 38448973, 2024). "In comparison to previously reported NF1 populations, we observed a significantly higher proportion of symptomatic spinal neurofibromas, dysmorphism, learning disabilities, malignancies, and skeletal and cardiovascular abnormalities in the present NF1-deleted cohort." (PMID 34199217, 2021). "To date, there has been little evidence suggesting genotype-phenotype correlation in NF1, except for NF1 patients with a NF1 microdeletion in which more severe clinical phenotypes, including a higher prevalence of learning disabilities and dysmorphic features, were found." (PMID 29618358, 2018). "The prevalence of learning disability appears indistinguishable between this genotype and classical NF1, demonstrating the importance of developmental assessment to allow for adequate support." (PMID 34897289, 2022).
metastatic disease (22 papers, 2014 to 2025). "Patients with BRAF and NF1 mutations appear to have the highest risk of brain metastases at the time of diagnosis of metastatic disease." (PMID 38339344, 2024). "Patients with BRAF or NF1 mutations were the only patients to present with brain metastases at the time metastatic disease was diagnosed." (PMID 38339344, 2024). "These alterations included genetic loss of the RAS-GAP NF1 (8% of metastatic tumors) and activating mutations in ERBB2 (7% of metastatic tumors)." (PMID 34795269, 2021). "Although the diagnosis of NF1 can be established by clinical findings, it is reported that 9.3% of patients with PCC/PGL caused by NF1 germline mutation suffer metastatic disease." (PMID 30613466, 2018). "Only one patient had metastatic disease (underwent CT) and one patient had NF-1 (underwent MT) in the series." (PMID 35586500, 2022). "Unilateral adrenal disease is most common (78-84%), with bilateral disease seen in only 9.6 to 16.6% of patients with PCC, and metastatic disease is seen in up to about 11.5% of patients, though these estimates are derived mostly from adult NF-1 patients." (PMID 35903274, 2022). "Several factors, such as metastatic disease; tumour grade, size, location, and surgical margin status; and NF1, have been indicated as significant prognostic predictors." (PMID 34867073, 2021). "Furthermore, identifying additional mutations, such as those in NF1 and ERBB2, highlights the genetic diversity and adaptability of metastatic tumors under selective pressure from endocrine therapies." (PMID 40075655, 2025). "Twenty-five patients had metastatic disease at the time of diagnosis (16 NF1, 9 sporadic)." (PMID 29138631, 2017). "In metastatic tumors, MEK inhibitors (selumetinib, trametinib) have shown great benefit in NF1 patients because they inhibit the MAP kinase pathway, which is overactivated due to NF1 mutation." (PMID 34025587, 2021). "Among the genes covered by this study, considering the 19 that are affected by alterations of any kind, only NF1 and ERF are found to be altered with significantly different frequencies between primary and metastatic tumor (adjusted p 0.016 and 0.025, respectively, FDR < 0.05 with 19 comparisons)." (PMID 36358725, 2022). "Additionally, over 10% of patients with NF1 and PHEO develop metastatic tumors, and most of these metastatic tumors are distant from the primary location." (PMID 30925729, 2019). "Second, whenever feasible, molecular profiling of the tumour (including assessment for somatic NF1 and other RAS-pathway alterations) can provide etiologic insight and may, in future, help identify targeted therapeutic opportunities for unresectable or metastatic disease." (PMID 41245174, 2025).
Li-Fraumeni syndrome (20 papers, 2018 to 2025). "Although ERMS can be associated with syndromes, such as neurofibromatosis 1 (NF1), Costello, Noonan or Li-Fraumeni syndrome, or as part of the DICER1 syndrome, sporadic cases are much more common." (PMID 34680895, 2021). "Three primary cancer predisposition syndromes known as Constitutional mismatch repair deficiency (CMMRD), Li-Fraumeni syndrome (LFS) and Neurofibromatosis-1 (NF-1) are some of many CPS which increase susceptibility to pHGG as a subsequent somatic mutation can initiate the onset of disease." (PMID 38525424, 2024). "Of the ten patients who screened positive and carried pathogenic germline mutations, eight fulfilled clinical criteria for CPS including Li-Fraumeni syndrome (LFS, n = 3), DICER1 syndrome (n = 3), neurofibromatosis type 1 (NF1) (n = 1) and von Hippel-Lindau (VHL, n = 1) syndrome." (PMID 30455982, 2018).
mucosal melanoma (20 papers, 2017 to 2025). A melanoma that arises from a mucosal site. "This study demonstrates that NF1 is the most frequently occurring driver mutation in mucosal melanoma." (PMID 28637487, 2017). "Our results underline that mucosal melanomas are genetically distinct from cutaneous and uveal melanomas with frequent inactivating mutations in NF1 and activating mutations in RAS genes." (PMID 28380455, 2017). "In addition, co-mutations of KIT and NF1 have been reported in mucosal melanoma, although they are rare." (PMID 34102999, 2021). "Our study identifies NF1 as the most frequently occurring driver mutation in mucosal melanoma." (PMID 28380455, 2017). "Oncogenic driver events are also found in the majority (93%) of anorectal melanomas with NF1 in 20% of cases and SF3B1 mutations as a recurrent genetic event in mucosal melanomas." (PMID 31466283, 2019). "In fact, alterations to driver genes such as SF3B1 and NF1 are relatively common in mucosal melanoma." (PMID 31466283, 2019). "Major driver mutations in mucosal melanoma were detected in NRAS, KRAS, NF1, PTEN, GNAQ, and KIT." (PMID 39564955, 2024). "NRAS and NF1 are confirmed to play a role in mucosal melanoma." (PMID 35159047, 2022). "NRAS and NF1 play a role in the molecular landscape of mucosal melanoma." (PMID 35159047, 2022). "Kit mutations occur in 7–10% of mucosal melanoma, and are observed not in association with NF1, RAS, or BRAF mutations; interestingly, Kit mutations are particularly frequent in vulvar melanomas." (PMID 29156643, 2017). "The frequent commutation of NF1 and Kit in mucosal melanomas was also observed." (PMID 29156643, 2017). "When the mucosal melanoma is triple (BRAF, NRAS, NF1)-negative, KIT is the most commonly mutated gene in vulvovaginal melanomas, while APC and KRAS are detected mainly in sinonasal and anorectal melanomas, respectively." (PMID 34571863, 2021).